TUSC3 (tumor suppressor candidate 3)
Diseases named in the same sentence as TUSC3 in open-access papers (continued):
Sharing a sentence is not in itself a finding about the gene and the disease.
preeclampsia (2 papers, 2009 to 2018). Preeclampsia is a hypertensive disorder of pregnancy that is characterized by new-onset hypertension with proteinuria presenting after 20 weeks of gestation, and depending on mild or severe forms may initially present with severe headache, visual disturbances, and hyperreflexia. "Further studies are necessary to confirm this association and to identify the intrinsic function of TUSC3 in the human placenta and its relation to preeclampsia development." (PMID 19838307, 2009). "Furthermore, TUSC3 promoter methylation showed evidence for association with preeclampsia." (PMID 19838307, 2009). "The correlation of TUSC3 promoter methylation with preeclampsia, a pregnancy disorder that is complicated by placental hypoxia implies a biological relevance to MAP." (PMID 19838307, 2009). "In particular, the expression of TUSC3 was downregulated in trophoblast upon hypoxic (a characteristic feature in preeclampsia) in vitro culturing." (PMID 19838307, 2009). "Specifically, TUSC3 promoter methylation was found more frequently in the late-onset preeclampsia than normal placentas (P = 0.02; Fisher's test)." (PMID 19838307, 2009).
autosomal recessive intellectual disability (1 paper, 2021). "Defects in the tumor suppressor candidate 3 (TUSC3) gene have been identified in individuals with autosomal recessive intellectual disability (ARID)." (PMID 34646667, 2021).
benign adenomas (1 paper, 2017). "We demonstrate that TUSC3 is epigenetically silenced already in benign adenomas, and loss of TUSC3 protein expression correlates with poor survival in early stages of CRC." (PMID 29156678, 2017). "TUSC3 mRNA expression was silenced by promoter methylation in 85 % of benign adenomas (n=46 cases) and 35 % of CRCs (n =74 cases)." (PMID 29156678, 2017). "First, we aimed to validate the presence of TUSC3 methylation in CRC tissues, to study its prevalence and occurrence in the adenoma-carcinoma-sequence as well as putative associations with clinical factors." (PMID 29156678, 2017). "Furthermore, methylation in adenomas indicated that silencing of TUSC3 is an early event in CRC carcinogenesis." (PMID 29156678, 2017). "We also measured methylation of the TUSC3 gene in patients with adenomas using ML-PCR." (PMID 29156678, 2017).
choriocarcinoma (1 paper, 2012). An aggressive malignant tumor arising from trophoblastic cells. "Loss of the 8p23.3p12 region, previously reported in primary choriocarcinoma, harbored (i) the CTSB gene, a cathepsin implicated in invasion and metastasis and (ii) DLC1 and TUSC3, two tumor suppressor genes that are expressed in the placenta, and often deleted in many cancers." (PMID 22253721, 2012).
hemochromatosis (1 paper, 2017). A disorder of iron metabolism characterized by a triad of HEMOSIDEROSIS; LIVER CIRRHOSIS; and DIABETES MELLITUS. "rs9393682 is located in the intergenic region between HIST1H1C (histone cluster 1 H1 family member c) and HFE (hemochromatosis), and rs1378033 is located in the intron of SGCZ (sarcoglycan zeta) and 5′ of TUSC3 (tumor suppressor candidate 3)." (PMID 29088772, 2017).
Hypertension (1 paper, 2009). The presence of chronic increased pressure in the systemic arterial system. "While the function of TUSC3 in placenta is unknown, its paralog, MAGT1, is believed to be associated with embryonic implantation and hypertension." (PMID 19838307, 2009).
leukemia (1 paper, 2021). A malignant (clonal) hematologic disorder, involving hematopoietic stem cells and characterized by the presence of primitive or atypical myeloid or lymphoid cells in the bone marrow and the blood. "CALN1 has previously known to be overexpressed in ETV6-RUNX1 leukemia but its exact function is still unknown, while TUSC3 is reported to be a tumor suppressor gene." (PMID 33708624, 2021).
metastatic cancer (1 paper, 2018). A carcinoma which has spread from the original site of growth to another anatomic site. "TUSC3 mRNA expression using qRT-PCR analysis were found to be reduced in metastatic cancer patient tissues compared to primary and/or normal lung tissues." (PMID 30504895, 2018).
microcephaly (1 paper, 2011). A congenital or acquired developmental disorder in which the circumference of the head is smaller than normal for the person's age and sex. "This region contained a total of 96 known genes {UCSC Genome Browser, May 2004 (NCBI35/hg17)} including MCPH1 and TUSC3, which have already been reported to be involved in microcephaly with ID." (PMID 21513506, 2011). "Also one gene for microcephaly (MCPH1) and one gene for NS-ID, namely TUSC3, have been identified on 8p." (PMID 21513506, 2011).
obsessive-compulsive disorder (1 paper, 2020). A disorder characterized by the presence of persistent and recurrent irrational thoughts (obsessions), resulting in marked anxiety and repetitive excessive behaviors (compulsions) as a way to try to decrease that anxiety. "TUSC3 is a GWAS locus for mental health disorders and general cognitive ability including educational attainment and mathematical ability, obsessive-compulsive disorder, and schizophrenia." (PMID 32653021, 2020).
oral cancer (1 paper, 2024). "We analyzed the expression of TUSC3 in established cell lines of oral cancer (Cal-27) against normal cells (HGF-1), to check whether this gene has some different pattern of expression in both conditions or not." (PMID 38992585, 2024).
peripheral nerve injury (1 paper, 2022). Injury to a peripheral nerve. "Consistent with the expression changes of MOGS, the expressions of many metabolism-associated genes, including DDOST, TUSC3, STT3A, STT3B, RPN1, MAGT1, and GANC, were elevated after peripheral nerve injury." (PMID 35575968, 2022).
renal cell carcinoma (1 paper, 2024). "TUSC3 has been reported as a potential biomarker in renal cell carcinoma." (PMID 38992585, 2024).
retinoblastoma (1 paper, 2021). A malignant tumor that originates in the nuclear layer of the retina. "Inhibition of miR-320a alleviates the proliferation and induces apoptosis of retinoblastoma cells through the pathway involving TUSC3." (PMID 35201481, 2021).
squamous cell carcinoma (1 paper, 2016). A carcinoma arising from squamous epithelial cells. "We found that RSPO3, ADAMTS8, DMBT1 and DOCK8 were all downregulated in squamous cell carcinoma tissues compared to non-cancerous lung tissues, whereas STMN2, TUSC3 and C8orf22 were upregulated in squamous cell carcinoma (all P < 0.001)." (PMID 27980454, 2016).
stomach adenocarcinoma (1 paper, 2021). "The bioinformatics analysis was performed to examine the expression status of cancer associated genes in patients with stomach adenocarcinoma (STAD) and predict the targeting sites of miR-224-5p with LncRNA MIR503HG and TUSC3." (PMID 34381729, 2021).
tumor (41 papers, 2008 to 2025). "in 48/125 (38.4%) blood and 54/138 (39.1%) tumor samples, and variant rs78999285 within the Alu element in TUSC3 was undefined in 60/125 (48.0%) blood and 62/138 (44.9%) tumor samples." (PMID 39770638, 2024). "Our findings suggested that expression of TUSC3 was down-regulated and significantly associated with poor differentiation, ascent of tumor size, and high level in BCLC stage." (PMID 36274132, 2022). "Since N-glycosylation is critical to the proper folding of the overwhelming majority of membrane and secreted proteins, it is most probable that loss of TUSC3 in tumors has pleiotropic effects that act additively to promote tumor growth." (PMID 29156678, 2017). "Low TUSC3 expression was associated with larger tumor size (p = 0.039), higher serum CA199 level (p = 0.034), more lymphatic permeation (p = 0.031), and higher Ki-67 labeling index (p<0.001)." (PMID 26871953, 2016). "This list includes PLA2G4A, HMGA2, TAGLN and TUSC3, all of which have been implicated in other neoplasias." (PMID 23046790, 2012). "Our findings demonstrated that HCMV-encoded miR-UL112-3p might act as a tumour regulator by directly targeting TUSC3 in GBM." (PMID 28303930, 2017). "The remaining three genes (e.g., CADM1, SPINK5 and TUSC3) were identified as tumor suppressor genes." (PMID 36675007, 2023). "TUSC3 has been characterized as a candidate tumour suppressor gene, which acts as an important signalling hub that modulates a variety of cellular processes." (PMID 35137520, 2022). "In this study, the expression of TUSC3 was downregulated in HCC tissues, and the expression of TUSC3 in HCC tissues were inversely related to tumor size, degree of differentiation, and BCLC stage." (PMID 36274132, 2022). "As TUSC3 has also previously been suggested as a potential tumour suppressor gene, in part due to its frequent hypermethylation, we also assessed any negative impact on the growth of re-expression of the gene in the TUSC3-deficient NALM6 cell line." (PMID 34230614, 2021). "Tumor-suppressor candidate 3 (TUSC3), also called Oligosaccharyltransferase 3 Homolog A, is closely related to tumor development." (PMID 34733314, 2021). "Our data solved this academic issue, and provided evidences to support that TUSC3 acted as a tumor suppressor to inhibit GC progression." (PMID 34381729, 2021). "Conversely, genes with known tumor-suppressor properties were identified among the genes overexpressed in TumLOW cells (e.g. TUSC3, SERPINB1)." (PMID 31619292, 2019). "We believe that the differential regulation of the three pathways was to protect the cells from excessive UPR activation suppressing tumor progression and metastasis, which makes TUSC3-dependent UPR oncogenic." (PMID 30504895, 2018). "The results in our study suggested TUSC3 as a tumor suppressor gene, which was in consistent with a recently published study." (PMID 29790668, 2018). "The downregulation of TUSC3 protein was further confirmed by immunohistochemistry using 50 sets of the primary and its corresponding metastasized tumor samples." (PMID 30504895, 2018). "Related to its candidate tumor suppressor function, the TUSC3 protein localizes to the endoplasmic reticulum and is involved in protein glycosylation, enabling it to inhibit cell proliferation and promote both apoptosis and autophagy." (PMID 30018746, 2018). "Immunohistochemistry analysis showed that the expression of TUSC3 levels in tumours with low miR-UL112-3p expression was significantly higher than those in tumours with high miR-UL112-3p expression." (PMID 28303930, 2017). "TUSC3 is a defined tumour suppressor gene and methylation usually occurs in its CPG island promoters." (PMID 28272772, 2017). "Early in 2005, Pils 30 reported that expression of TUSC3 was lower only in tumours of advanced grade (significant), FIGO (the International Federation of Obstetricians and Gynecologists) stages and in patients with relapse (trends not significant)." (PMID 28272772, 2017).
tumor (continued). "The expression of TUSC3 is dramatically decreased in metastatic LNs compared with the paired primary tumor samples (H-score: p<0.001)." (PMID 26871953, 2016). "To further explore the effect of TUSC3 on PC metastasis, we injected TUSC3 silenced tumor cells orthotopically into pancreas in nude mice and established animal models." (PMID 26871953, 2016). "From the pictures we can apparently see the liver metastasis of TUSC3 silenced tumor is bigger than the control one." (PMID 26871953, 2016). "A number of these genes are of apparent interest for GBM biology such as TUSC3, which is a tumor suppressor candidate gene and known to be hypermethylated in GBMs." (PMID 23658659, 2013). "We therefore combined the expression values for the genes identified above (DDIT3, HOXD10, PDE1C, PLS3, PTEN and TUSC3) into a single value per tumor sample, termed 'GNS signature score'." (PMID 23046790, 2012). "This identified six tumours that had completely lost expression of TUSC3, and a further thirteen that expressed it at a lower level than the range observed in normal breast luminal and basal cells." (PMID 18840272, 2008). "Numerous studies report TUSC3-mediated tumor progression in various malignancies." (PMID 37834755, 2023). "Survival analysis revealed that TUSC3 downregulation was associated with poor OS (p = 0.001) and PFS (p = 0.012) in 136 patients with stage I, but not with OS (p = 0.132) and PFS (p = 0.118) in 84 patients with stage II tumours." (PMID 35137520, 2022). "The significantly regulated genes identified in both KYSE150 and KYSE410 cells were found to be involved in cell adhesion (PCDH family genes, CLDN1, CNTN1), cell apoptosis (MAPK10/JNK3, PYCARD), tumor suppression (TUSC3, SAMD9L) and immunity regulation (IFNL3)." (PMID 32089740, 2020). "Data mining for 5′-end CpG island methylation of TUSC3, ATRNL1, POMT1 and SAMD4A in cancer cell lines and primary tumors showed that the epigenetic defect was commonly observed among different tumor types in association with the diminished expression of the corresponding transcript." (PMID 30018746, 2018). "Loss of TUSC3 leads to increased proliferation, viability, migration, and invasion of DU145 and PC3 cells, which is accompanied by elevated N-glycosylation and AKT phosphorylation, indicating that TUSC3 exerts its tumor suppressor activity by influencing these processes." (PMID 27303918, 2016). "All these results suggest TUSC3 expression may be regulated by NF-κB activity, at least in some tumor cell lines." (PMID 26871953, 2016). "It is also possible that TUSC3 expression may be regulated by different means even in the same tumor type depending on different patients or cell lines." (PMID 26871953, 2016). "It is possible that TUSC3 down-regulation mechanisms vary according to different tumor types." (PMID 26871953, 2016). "More and larger colonies formed for TUSC3 silenced tumor cells." (PMID 26871953, 2016). "Therefore, TUSC3 gene was originally assumed to be a tumor suppressor candidate." (PMID 36274132, 2022). "Furthermore, TUSC3 may modulate the activity of the AKT signalling pathway to promote tumour progression and metastasis." (PMID 35137520, 2022). "Interestingly, some genes were already known to have a biological role in tumourigenesis, either as tumour suppressors (such as TUSC3) or elements of critical importance within tumour growth pathways (i.e., SFRP1 and FZD6, belonging to the Wnt signalling pathway)." (PMID 35327445, 2022). "However, target glycoproteins that are affected by the loss of TUSC3 and are responsible for tumor progression have not been identified." (PMID 31810196, 2019). "Thus, TUSC3 circ104557 acts in our model as an inhibitor of tumor growth." (PMID 30018746, 2018).
tumor (continued). "We demonstrate that TUSC3 reduced tumor cell viability and enhanced apoptosis, an effect which may be in part attributed to the ability of TUSC3 to inhibit phosphorylation and down-stream signaling of the EGFR together with additional oncogenic pathways including ERK1/2, hypoxia and Wnt signaling." (PMID 29156678, 2017). "Silencing of tumor suppressor candidate 3 (TUSC3) mRNA expression by promoter hypermethylation induces upregulation of the epidermal growth factor receptor (EGDR), leading tumor cell resistance to apoptosis." (PMID 38255288, 2024). "An in-silico analysis and luciferase assay identified miR-224 and miR-520c as suppressors of tumor suppressor candidate 3 (TUSC3), related to tumor procession." (PMID 34199614, 2021). "In the multivariate analysis, copy-number losses (CNLs) in chromosome B1 (1–23 Mb) harbouring several tumour-repressors (e.g. CSMD1, MTUS1, MSR1, DBC2, and TUSC3) negatively influenced DFS." (PMID 31969654, 2020). "On the other hand, common CNLs negatively influencing survival intervals harboured important tumour suppressors (e.g. CSMD1, MTUS1, MSR1, DBC2, and TUSC3) and genes enriching biological processes that would normally prevent cellular movement." (PMID 31969654, 2020). "Methylation inactivation of tumor suppressors such as UCHL1 and TUSC3 were diagnosed with EOC.IFI27 was responsible for the proliferation of epithelial cancer cells.Li IFI27 was associated with invasion and drug resistance in EOC." (PMID 30970615, 2019). "Suppressing TUSC3 expression has a large impact on the morphology and homeostasis of the ER and promotes EMT and tumor growth." (PMID 31810196, 2019). "It was discovered that miR-UL112-3p targets tumor suppressor candidate 3 (TUSC3), a putative tumor suppressor gene, proving that miR-UL112-3p may function as a tumor regulator by specifically targeting TUSC3 in GBM." (PMID 36851643, 2023). "On the other hand, CNLs in FCA B1 1–23 Mb (human homologue region located in HSA 8p) were significant in multivariate analysis and harboured multiple tumour suppressors (e.g. CSMD1, MSR1, MTUS1, and TUSC3) previously correlated with poor prognosis in HBCs15,19,23,27,70." (PMID 31969654, 2020). "Of note, TUSC3 was localized to mononuclear blood cells as a positive control, but was also found in the tumor and stroma (non-epithelial) compartments of CRC tissue." (PMID 29156678, 2017). "Although it is possible that TUSC3’s involvement in N-glycosylation varies according to caner type and N-glycosylation does play a role in cancer initiation and progression, it is also possible that its tumor suppressor role is not directly related from its involvement in N-glycosylation." (PMID 26871953, 2016). "TUSC3 methylation was confirmed by next generation sequencing (NGS) in a small series of matched non-tumor (NT) colon and tumor (TU) samples from CRC patients." (PMID 29156678, 2017).